INS (insulin)
Diseases named in the same sentence as INS in open-access papers (continued):
Sharing a sentence is not in itself a finding about the gene and the disease.
diabetes (continued). "Insulin pumps offer the best diabetes control, but their high cost makes them unaffordable to many." (PMID 39065641, 2024). "Many studies have shown that vitamin D can reduce the occurrence of diabetes and delay the progression of diabetes complications, and vitamin D can reduce oxidative stress, inhibit iron apoptosis, promote Ca2+ influx, promote insulin secretion, and reduce insulin resistance." (PMID 38650715, 2024). "The detection of some level of insulin secretion in the diabetes group suggests that the dose (45 mg/kg STZ) we used for inducing pancreatic beta cell damage did not cause complete and absolute destruction but rather indicates the presence of residual surviving cells." (PMID 38726421, 2024). "The KK-Ay/Ta mice were reported to increase levels of plasma insulin and to decrease levels of plasma adiponectin compared to healthy mice, suggesting that reversal of these effects may contribute to diabetes prevention." (PMID 38392186, 2024). "Additionally, miRNAs have been extensively studied in diabetes, where they are involved in regulating insulin secretion, sensitivity, and β cell function." (PMID 39220230, 2024). "Patients with diabetes have many misconceptions about insulin that cause them not to adhere to insulin therapy." (PMID 38694587, 2024). "Finally, patients with diabetes with occupation (β = 0.134, p < 0.001), with family history of diabetes (β = 0.150, p < 0.001) and using insulin (β = 0.166, p < 0.001)." (PMID 38751583, 2024). "Insulin treated patients showed more knowledge about which symptoms are not usually associated with diabetes (DKT-14)." (PMID 38525337, 2024). "Such notion is further supported by another general practice study, reporting higher insulin initiation-rates and better glycemic control with an intervention with a practice nurse who, assisted by a nurse with formal diabetes competences, led all insulin initiations." (PMID 38116986, 2024). "However, patients with diabetes were over ten times as likely to return to IV insulin drip in our study." (PMID 39590191, 2024). "In the present study, several measures of insulin resistance and hyperinsulinemia associated with incident AS if diabetic subjects were excluded, suggesting that insulin is an important risk factor for AS in all subjects independent of diabetes." (PMID 39593205, 2024). "Understanding these mechanisms could offer valuable insights for design of novel, long-lasting insulin analogs, ultimately providing enhanced convenience for diabetes patients." (PMID 38182007, 2024). "In addition, comparable to the respondents from GEDA 2021/2022-Diabetes, around one third are treated with insulin (alone or in combination with other medications) and there are no sex-related differences." (PMID 39081466, 2024). "Consequently, identifying novel agents that mimic or enhance the effect of insulin on oral consumption is crucial for improving diabetes treatment." (PMID 38675446, 2024). "Some variables could not be quantified (e.g., the number and frequency of cigarettes smoked, whether diabetes is insulin-dependent, the lasting days of temporary external fixator use), or their severity could not be assessed (e.g., soft tissue damage)." (PMID 38586239, 2024). "For those diabetic patients, SIPs when combined with CGM and an insulin dosing calculator represent a new category of diabetes management – the smart insulin pen system – for those managing their insulin with multiple daily injections (MDI) and can provide many of the benefits of an AID system." (PMID 39411309, 2024). "Moreover, SAP-associated diabetes is a complication of SAP characterized by persistent hyperglycemia and requires management through lifestyle changes, medication, and insulin therapy." (PMID 38481805, 2024). "Diabetes duration was 19 ± 11 years, and insulin TDD/kg of body weight was 0.63 ± 0.19 units/kg." (PMID 39274516, 2024).
diabetes (continued). "Alternatively, new functions may have nothing to do with virulence and can be utilitarian and non-controversial, such as having bacteria or yeasts express the hormone insulin that is used to treat diabetes." (PMID 38132562, 2024). "Diabetes mellitus might occur when pancreatic beta cells are unable to secrete any or very little insulin, due to insulin insensitivity in the body." (PMID 39534260, 2024). "In a cohort of patients who underwent epiretinal membrane surgery, neither the presence of diabetes, nor glycemic control and the use of insulin medication associated with the outcomes." (PMID 39636335, 2024). "Individuals with diabetes mellitus may have to maintain their financial stability in managing their diabetes treatment, especially oral medications and insulin regimens." (PMID 39405517, 2024). "This difference could be explained by the severity of β-cell damage in the STZ model and the poor insulin response in the peripheral organs of HFD + STZ diabetes-induced rats." (PMID 38673735, 2024). "Diabetes of various etiologies is characterized by a decrease in insulin expression." (PMID 39045459, 2024). "However, the obesity paradox was less pronounced in patients with diabetes treated with insulin and it disappeared in those with poor glycaemic control as defined by HbA1c levels > 7.5%." (PMID 37608126, 2024). "In addition, the distinct hypoglycemic effects observed in different diabetes models highlight the possibility of tailoring insulin therapies to specific types of diabetes or patient needs." (PMID 38535452, 2024). "Accordingly, insulin needs late in pregnancy could be an indicator of who will later develop diabetes." (PMID 38601785, 2024). "Thus, GSH is crucial for both β-cell function and insulin sensitivity, with its depletion representing a significant factor in diabetes pathogenesis." (PMID 39857603, 2024). "In 2 patients with Rabson–Mendenhall syndrome with diabetes of long duration (>3 years) and modest or null response to metformin and insulin therapy, the SGLT2i empagliflozin (5 mg) was introduced as an add-on treatment with good to excellent results (manuscript in preparation)." (PMID 38408297, 2024). "Insulin-secreting cells generated from stem cells or through genetic engineering of various cell types have emerged as advanced alternative therapeutic strategies for diabetes." (PMID 39279997, 2024). "The majority of the cases are type 2 diabetes mellitus (T2DM), a complex condition characterised by a deficiency in the insulin secretion by β-cells of the pancreas, tissue insulin resistance (IR) along with an insufficient compensatory insulin secretory response." (PMID 39100011, 2024). "Background/Objectives: Diabetes mellitus (DM) is a complex and heterogenous disease classified as a group of metabolic disorders characterized by chronic hyperglycemia resulting from defects in insulin secretion, insulin action, or both." (PMID 39598447, 2024). "Diabetes mellitus (DM) is a syndrome of multiple etiologies characterized by chronic hyperglycemia with disturbances of carbohydrate, fat, and protein metabolisms resulting from defects in insulin secretion, insulin action, or both." (PMID 39077252, 2024). "Therefore, it shows a more positive effect in all three primary target insulin groups to improve insulin resistance and its potential to prevent and treat diabetes." (PMID 38799166, 2024). "Future studies could determine whether similar levels of elevated angiotensin 2 could decrease insulin production and induce diabetes." (PMID 38400070, 2024). "The ATTICA study reported that adherence to the Mediterranean diet was associated with enhanced fasting glucose homeostasis, insulin levels, and a more favorable insulin resistance index (HOMA) in both those with normal blood sugar levels and those with diabetes." (PMID 38800782, 2024).
diabetes (continued). "First, one SWEET registry study examined use of diabetes technology (insulin pumps, continuous glucose monitors) across 101 SWEET centers, showing that > 60% of the 25,654 pediatric T1D patients used at least one technological component for diabetes management." (PMID 39470899, 2024). "Amongst 209 individuals with diabetes, 186 were considered to have type 2 as they were treated by oral antihyperglycemic agents, including 23 men who were treated with a combination of antihyperglycemic agents and insulin." (PMID 38829475, 2024). "The PRISMA (Prospective, Randomized Trial on Intensive Self-Monitoring Blood Glucose Management Added Value in Non-Insulin Treated Type 2 Diabetes Mellitus Patients) trial demonstrated that intensive SMBG significantly enhances glycemic control and aids in managing type 2 diabetes." (PMID 39507142, 2024). "I shared my challenges with managing diabetes and my fear about starting the insulin pump." (PMID 39539363, 2024). "Since methylation is a complex issue related to ageing, insulin sensitivity, and diabetes complications, we compared the PRS constructed from genotype data and found non-significant differences between AO-exposed and AO-unexposed individuals with type 2 diabetes." (PMID 39072272, 2024). "Additionally, the chronoamperometric response curves of three distinct groups of rats with diabetes were measured: rats injected with 5 IU insulin, rats injected with 1 IU insulin, and rats which fasted for 12 h." (PMID 38248422, 2024). "However, when this compensatory mechanism is overwhelmed, insulin resistance escalates to prediabetes and eventually leads to a reduction in insulin secretion, culminating in overt diabetes." (PMID 38904045, 2024). "In particular, both OA in vitro and OO in vivo showed superior activities on protecting islets function and enhance insulin sensitivity, suggesting that MUFAs might have greater potential for nutritional intervention on diabetes." (PMID 38501107, 2024). "Diabetes knowledge level was influenced by per capita household disposable income, occupational status, gender, age, ethnicity, family history of diabetes, insulin use, glycated hemoglobin, education level, number of complications and health information-seeking behavior." (PMID 38751583, 2024). "However, the limited functional maturation (impaired GSIS) of hPSC-derived insulin-expressing β-cells emanating from those protocols hampers the current strategies of cell replacement therapy for diabetes." (PMID 38966213, 2024). "Pancreatic cancer often causes diabetes, considered as type 3c diabetes when pancreas fails to produce sufficient insulin." (PMID 39333445, 2024). "However, early and late treatments with WJMSCs-CM and insulin significantly decreased the expression level of TNF-ɑ mRNA compared to the untreated diabetes group." (PMID 39391856, 2024). "However, The Master Plan would benefit people with diabetes if it can support the establishment of companies manufacturing insulin and SMBG devices." (PMID 39361609, 2024). "Insulin responses to the MMTT were a consistent predictor of incident diabetes." (PMID 38987291, 2024). "Thus, central hypoglycaemia sensing relies on a variety of signalling pathways, and there is little information about the dysegulations that impair the counterregulatory response (CRR) in people with diabetes treated with insulin." (PMID 38017352, 2024). "These include a focus on key areas of research and clinical practice, such as the role of gut microbiota modifications in insulin production and glycemic control and research into the genetic basis of diabetes by allowing for more predictive analytics and precision medicine strategies." (PMID 39337311, 2024). "Early insulin initiation, optimisation and patient empowerment can help manage type 2 diabetes effectively but will require professional education and upskilling in the practical management of diabetes." (PMID 38572871, 2024).
diabetes (continued). "Among the study participants, 182 (44.0%) of them had a family history of diabetes mellitus, three-fourths (313.6%) of them were treated with oral anti-hyperglycemic drugs, and 13 (3.1%) of them took insulin injections, while 88 (21.3%) of the patients took both oral and injection drugs." (PMID 38756386, 2024). "After adjusting for confounders, PFNA and PFOA showed a significant non-linear relationship with diabetes mellitus.PFOA is associated with the insulinogen/insulin ratio but not with markers of insulin resistance." (PMID 38251002, 2024). "Diabetes mellitus type 1 (DM1) is a chronic metabolic disease caused by the autoimmune destruction of the insulin-producing β-cells in the pancreas, leaving the patients dependent on an external supply of insulin." (PMID 37715091, 2024). "Vitamin D supplementation has been linked in studies to better insulin sensitivity and beta cell activity in people at elevated risks for diabetes but not in people with normal baseline fasting glucose." (PMID 39822434, 2024). "Insufficient insulin secretion plays a pivotal role in the onset of diabetes." (PMID 39091901, 2024). "Cell-based therapy using insulin-producing cells (IPCs) is anticipated as an alternative treatment option to insulin injection or pancreatic islet transplantation for the treatment of diabetes mellitus in both human and veterinary medicine." (PMID 39195834, 2024). "Serum insulin exhibited a main effect of diabetes (F = 44.99, p < 0.0001)." (PMID 38435452, 2024). "The good residual endogenous insulin secretion (post-meal C-peptide level: 1150 pmol/L) 6 years after the diagnosis of type 1 diabetes was the main indicator prompting genetic testing for monogenic diabetes." (PMID 39420387, 2024). "The importance of insulin processing to β-cell function is evident from the numerous mutations in the human insulin gene leading to hormone misfolding, that cause mutant INS-gene-induced diabetes of youth (MIDY)." (PMID 38404962, 2024). "Sex-specific differences have been found in glucose homeostasis, insulin secretion and action, and the incidence and progression of diabetes, which might help explain this different distribution." (PMID 39196799, 2024). "Notably, known diabetes [31 (41.3%) vs. 11 (11.5%), P < 0.001], insulin usage [7 (9.3%) vs. 0 (0.0%), P = 0.008], and biguanides usage [7 (9.3%) vs. 1 (1.0%), P = 0.029] were more frequent in AMI patients with hyperglycemia than in those without hyperglycemia." (PMID 38902730, 2024). "However, non-insulin therapy seems beneficial in patients where diabetes recurs, but we recommend close follow-up to ensure treatment intensification if patients do not reach or remain stable at their glycemic target (grade D evidence)." (PMID 39025920, 2024). "Secondly, conducted in 5994 men (≥65 years), found that non-vertebral fracture risk was higher in patients with diabetes who were using insulin compared with non-diabetic patients (HR1.74; 95%CI:1.31–2.69)." (PMID 39735781, 2024). "Diabetes mellitus (DM) is a metabolic disorder characterized by hyperglycemia, which can be caused by either a decrease or absence of insulin secretion, increased resistance, or both." (PMID 39840159, 2024). "In Korea, the diabetes awareness rate—defined as the percentage of individuals diagnosed with diabetes by a doctor among those with the disease—was 66.6%, with 62.4% being treated with glucose-lowering agents or insulin." (PMID 38993111, 2024). "In the diabetes group, fasting insulin AUC was significantly lower than the AGE group (p < 0.05)." (PMID 38778421, 2024). "Pre-diabetes is characterized by IR, which is the inability of the body to respond to insulin." (PMID 38327565, 2024). "Elevating circulating insulin is believed to be a major factor linking diabetes and cancer." (PMID 39410536, 2024). "Therefore, the use of the hypoglycaemic drug metformin in combination with insulin is recommended to limit weight gain in patients with diabetes." (PMID 38686463, 2024).
diabetes (continued). "Also, the reduced abundance of butyrate-producing bacteria and SCFAs, particularly butyrate, has been directly associated with type 2 diabetes mellitus (T2DM), owing to its connection with insulin sensitivity." (PMID 38786121, 2024). "Silibinin might also enhance insulin secretion from pancreatic beta cells, which could assist in controlling blood glucose levels and alleviating the effects of diabetes." (PMID 38726421, 2024). "By making specific aspects of diabetes management easier, such as glucose monitoring, insulin delivery, or refilling prescriptions, these technological advances decrease the overall load of diabetes management and make it more possible for an individual to manage independently." (PMID 38774897, 2024). "Yet, in LMICs such as Ghana, young people living with T1DM face structural barriers including lack of specialist care, insufficient delivery services, erratic supply or excessive costs of life-saving insulin, and other diabetes management logistics such as test strips which remain unobtainable." (PMID 38178122, 2024). "Diabetes mellitus is a chronic condition caused by either a lack of insulin production (T1D) or insulin resistance (T2D), leading to elevated blood glucose levels." (PMID 39411309, 2024). "In participants with diabetes, use of insulin was predominantly in small %TBSA." (PMID 38791089, 2024). "There have been several studies demonstrating that fenugreek (Trigonella foenum-graecum) can improve glycemic control in individuals with diabetes by reducing blood glucose levels and improving insulin sensitivity in obese and overweight patients with T2DM and non-insulin-dependent diabetics." (PMID 39000103, 2024). "Metformin, which is a biguanide family drug that is used in the treatment of diabetes, that reduces the glucose level and improves insulin sensitivity in peripheral tissues, may also have an anti-cancer effect." (PMID 38254789, 2024). "Using the CC genotype as a reference point, there was no notable variation in GDM risk was observed across different FokI VDR genotypes, even after adjusting for vitamin D deficiency, HbA1c, fasting serum insulin, previous history of GDM, obesity, BMI, age, and family history of diabetes." (PMID 38882352, 2024). "Insulin replacement therapy is essential for the management of diabetes." (PMID 37697741, 2024). "Kcnk16 L114P may not cause a significant β-cell destruction because these mice show sufficient glucose-stimulated insulin secretion to prevent overt diabetes." (PMID 38700926, 2024). "Compared with the general population of patients with type 2 diabetes, the study population appears to have less advanced disease due to the exclusion of people with diabetes taking insulin and patients with diagnosed micro- and macro-vascular diabetes complications." (PMID 38778308, 2024). "The patients have long-standing diabetes and a mean duration of insulin injection of 7 years." (PMID 39020348, 2024). "The aim of the study was to understand whether decreases in weight and IR or hormonal (insulin, glucagon, and incretin) changes lead to diabetes remission after bariatric surgery." (PMID 39598143, 2024). "Type 1 diabetes mellitus (T1DM) is a wasting disease characterized by severe deficiency or absence of insulin." (PMID 38724932, 2024). "Diabetes mellitus (DM) refers to chronic metabolic disorders characterized by hyperglycemia as a consequence of insulin dysfunction, either due to defects in insulin secretion, insulin action, or both." (PMID 39334905, 2024). "Additionally, an impaired insulin function in diabetes disrupts glycogen synthesis and storage, leading to abnormal glucose metabolism and further exacerbating the metabolic imbalance." (PMID 39323638, 2024). "In addition to the metformin treatment, 37.75% of patients received other diabetes-related medications, insulin (18.5%) and other oral hypoglycemic agents (19.2%), while the majority (62.2%) with metformin prescription only." (PMID 39310418, 2024).